ALB (albumin)
Diseases named in the same sentence as ALB in open-access papers (continued):
Sharing a sentence is not in itself a finding about the gene and the disease.
cyst (20 papers, 1994 to 2025). A sac-like closed membranous structure that may be empty or contain fluid or amorphous material. "The reduction of the size of the parasite likely results from treatment-induced cyst damage and associated increased permeability of the cyst membrane, with a consequent increase in density of the cyst contents due to the influx of host albumin, protein coagulation, and loss of water." (PMID 28575043, 2017). "Clinical factors associated (p < 0.05) with an increased risk of malignancy included cyst size greater >3 cm (OR (95% CI) = 2.60 (0.76–8.86, p = 0.127), main duct involvement (OR (95% CI) = 11.00 (2.26–53.63, p = 0.003), and serum albumin levels (OR (95% CI) = 0.35 (0.11–1.15, p = 0.083)." (PMID 28874676, 2017). "This article shares our experiences with the therapeutic effects of albumin-coated bone allograft (BoneAlbumin®) placed in the bone defect following cyst removal in the oral cavity, compared to cases where the defect was left untreated (controls)." (PMID 40565919, 2025). "In agreement with previous studies, sitagliptin produced a significant decrease in serum urea, creatinine, MPO, and cyst-C levels while preserving serum albumin compared to the nephrotoxicity group of rats." (PMID 38548778, 2024). "Sodium and potassium were similar in cyst fluid and serum, but the total concentration of calcium was lower in cyst fluid, probably reflecting the lower level of albumin, which carries calcium." (PMID 35659255, 2022). "In addition, the extent of renal involvement might play a role in the development of blood pressure rise and arterial damage as blood pressure was associated with cystatin C and cyst diameter and aortic pulse wave velocity with urine albumin loss and AML diameter." (PMID 34912759, 2021). "Such comparison resulted in 4 upregulated (CP, CEACAM5, DMBT1, and KRT6A) and 8 downregulated (CEL, CPA1, CPB1, ALB, SERPINA4, CA2, CLU, and AMBP) DEGs secreted in cyst fluid of high-risk IPMNs." (PMID 34790815, 2021). "Abundant host proteins such as IgG and albumin were detected in the three protein fractions tested (soluble and insoluble fraction of cyst ́s tissue and in the vesicular fluid)." (PMID 28945737, 2017). "Several peaks in the cyst fluid were identified as albumin and other proteins that also are abundant in blood." (PMID 23268721, 2012). "Finally, urinary albumin, maximum cyst diameter, eTKV and radiomics signature (Rad) were included to build the radiomics nomogram model by using logistic regression." (PMID 35152314, 2022). "The mean levels of albumin and apolipoprotein A-I in cyst fluid were 64% and 34% of those in serum, respectively, and the variability in concentration was greater in cyst fluid than in serum, as could be seen from the standard deviations." (PMID 35659255, 2022). "However, the ratio between cyst fluid and CSF for these three protein complexes was reduced (dependent on size), from 0.73 for protein (of which 2/3 albumin) to 0.31 for ferritin." (PMID 20537169, 2010). "Macromolecules such as albumin (67 kDa), ferritin (24 subunits between 19 and 21 kDa, total weight around 450 kDa) and lactate dehydrogenase (tetramer of about 37 kDa, total weight around 140 kDa) would be expected to pass freely through a slit in the cyst membrane." (PMID 20537169, 2010). "Duration of methylprednisolone treatment did not correlate with cyst fluid concentrations of apolipoprotein A-I (r = 0.03) or albumin (r = 0.005), but it correlated inversely with SHBG (r = − 0.50; p = 0.011)." (PMID 35659255, 2022). "To determine the protein profile of the cyst found in JNK1/2LPC-KO mice, we performed a mass spectrometry analysis, which also revealed a high content of proteins typical for serum samples like albumin, serotransferrin, complement 3, and various isoforms of α-1-antitrypsin." (PMID 33798093, 2021). "Similarly, the cyst fluid concentration of SHBG and albumin, both of which may carry testosterone, correlated with tumor volume." (PMID 35659255, 2022).
cyst (continued). "After they were expanded, hepatic progenitor cell cultures could undergo differentiation into hepatocyte-like cells that expressed ALB and AAT and stored glycogen, or into cholangiocyte-like cells that formed duct-like cyst structures, expressed KRT7 and KRT19 and acquired epithelial polarity." (PMID 19649295, 2009). "In the PC cyst group, proteomic profiles data was also collected, except for PC1, for which no protein was detected, except albumin." (PMID 33396529, 2020). "Neither control nor experimental mammary epithelia, including both Spry2Δ/Δ and Spry2-GOF epithelia, invaded toward beads pre-soaked in bovine serum albumin (BSA) or beads soaked in FGF2, which stimulate cyst formation (not shown), during the 72-hour time course." (PMID 24718286, 2014).
dyslipidaemia (20 papers, 2010 to 2025). "Dyslipidaemia was also associated with low serum albumin, with a p-value <0.001, which is statistically significant." (PMID 37869045, 2023). "Studies have shown that younger age, dyslipidaemia, lower albumin, lower Hb and proteinuria are associated with CKD progression and all these factors were predictive of patients having rapid linear progression in our analysis." (PMID 32795261, 2020). "The patients with dyslipidaemia had higher blood pressure, poorer renal function, more obvious haematuria, lower serum albumin, and more serious renal tubular interstitial damage." (PMID 33112407, 2020). "Several studies have shown that corticosteroid therapy improves the regeneration of podocytes and the restoration of the glomerular filtration barrier which may normalize albumin in serum and ameliorate dyslipidaemia." (PMID 35799985, 2022). "ApoA1, eGFR, haemoglobin (Hb), and albumin (Alb) were lower in the dyslipidaemia group than in the non-dyslipidaemia group (P<0.05, for each)." (PMID 33112407, 2020). "Compared with the non-dyslipidaemia group, the dyslipidaemia group exhibited higher blood pressure, blood urea nitrogen, uric acid, and body mass index; higher prevalence of oedema, haematuria, tubular atrophy, and interstitial fibrosis; and lower albumin and estimated glomerular filtration rate." (PMID 33112407, 2020).
enteropathy (20 papers, 2011 to 2025). "Albumin and cobalamin were significantly higher in food-responsive enteropathy, whereas the canine chronic enteropathy clinical activity index (CCECAI) was significantly higher in immunosuppressive-responsive enteropathy and non-responsive enteropathy." (PMID 40509037, 2025). "Cats with concurrent pancreatic and/or hepatic ultrasonographic alterations showed lower albumin, lower α-globulin, and higher γ-globulin levels than cats diagnosed with enteropathy alone." (PMID 36136669, 2022). "Previous studies report that serum albumin is a readily measured endogenous parameter of acute intestinal leakage in NSAID-induced enteropathy." (PMID 32443501, 2020). "Multiple endoscopic variables were taken into consideration in LPE dogs, according to standard criteria, and the endoscopic score was compared to the clinical and histological ones, as well as to laboratory variables suggesting protein-losing (albumin and cholesterol) enteropathy." (PMID 25584174, 2015). "A significant difference between NSAID users (RA and OA) with and without enteropathy was observed in erythrocytes (p < 0.01), the leucocyte count (p < 0.05), haemoglobin (p < 0.05), haematocrit (p < 0.05), serum albumin (p < 0.01) and erythrocyte sedimentation rate (p < 0.05)." (PMID 27549792, 2016). "However, her low albumin levels seem somewhat resistant to TPN and no other cause can be discerned, suggesting that the patient has protein loosing enteropathy, a known comorbidity to JPS." (PMID 25705527, 2015).
metastatic carcinoma (20 papers, 2011 to 2026). A carcinoma which has spread from the original site of growth to another anatomic site. "Cell‐free and concentrated ascites reinfusion therapy had lower mortality and in‐hospital costs than paracentesis in metastatic cancer, particularly in males, patients with serum albumin ≤ 2.5 g/dL, and those with non‐gastrointestinal cancer." (PMID 41454579, 2026). "CART was associated with improved clinical outcomes and healthcare costs over paracentesis among hospitalized patients with metastatic cancer, particularly in males, patients with serum albumin ≤ 2.5 g/dL, and those with non‐gastrointestinal cancer." (PMID 41454579, 2026). "In a subgroup analysis of patients with hematologic or metastatic cancer (n = 5), the median net albumin leakage was 0 g (range: − 4 to 31 g, p = 0.81), with a mean of 7 g." (PMID 40057738, 2025). "We leverage its lymphatic transport by binding drugs to albumin, offering more efficient and targeted therapies for metastatic cancers and autoimmune disorders." (PMID 39871825, 2025). "The decline in serum albumin among women with metastatic cancer was significantly greater than the decline among women with localized disease (22% vs. 12.7%; p > .01)." (PMID 32723677, 2020). "In conclusion, the available evidence demonstrates that albumin levels could be a promising prognostic biomarker in patients with metastatic cancer treated with immunotherapy." (PMID 36533070, 2022). "Importantly, significant changes in age- and storage-adjusted calcium and albumin were observed in women with localized as well as metastatic cancer." (PMID 32723677, 2020). "The top predictors shared across all models were most recent albumin and alkaline phosphatase levels and number of recent and total diagnostic codes for solid tumor without metastasis and metastatic cancer." (PMID 31651973, 2019). "Furthermore, we showed that the combination of PS and biological covariates such as LDH, lymphocyte and platelet counts, serum albumin and IL-6 levels is an effective strategy to predict survival for patients with advanced or metastatic cancer receiving further treatment after the first-line." (PMID 21406082, 2011). "In simulation 3, the basal value for KGin vivo, 19 uM, is used, and the plasma albumin and AGP concentrations are set at the levels observed in metastatic cancer, AF = 600 uM and GT0 = 70 nM." (PMID 36829100, 2023).
Peptic ulcer (20 papers, 2014 to 2025). The term peptic ulcer refers to acid peptic injury of the digestive tract, resulting in mucosal break reaching the submucosa. "GERD indirectly affected all-cause mortality through ileus, and peptic ulcer disease had indirect effects through albumin and ileus." (PMID 38831863, 2023). "Peptic ulcer disease indirectly affected all-cause mortality through albumin (β = −0.059) and ileus (β = 0.138)." (PMID 38831863, 2023). "A subgroup analysis of elderly and peptic ulcer patients found that serum albumin level was an independent risk factor of mortality in the overall analysis." (PMID 36568536, 2022). "Other independent risk factors for intractable endostasis in peptic ulcers include age ≥70 years, shock on hospital admission, hemoglobin <8.0 mg/dL, serum albumin <33 g/L, exposed vessels ≥2 mm diameter in the ulcer base and Forrest-type Ia and Ib lesions." (PMID 25991813, 2016). "We also found that GERD indirectly affected all-cause mortality through ileus, peptic ulcer disease indirectly affected all-cause mortality through low albumin and ileus, and that ileus indirectly affected all-cause mortality through low albumin and underweight." (PMID 38831863, 2023). "This retrospective study investigated the prognostic value of the red cell distribution width (RDW)‐to‐albumin ratio (RAR) in patients with peptic ulcer perforation." (PMID 39993970, 2025). "The aim of our study was to investigate the prognostic role of platelet/albumin ratio in patients treated under emergency conditions for peptic ulcer perforation (PUP)." (PMID 35945802, 2022). "Dialysis patients with peptic ulcer had lower serum albumin levels and higher blood urea nitrogen (BUN) levels than non-ulcer patients." (PMID 33092560, 2020). "Based on the established associations between elevated RDW and decreased albumin with poorer clinical outcomes, RAR may serve as a composite marker, reflecting prognosis in peptic ulcer perforation." (PMID 39993970, 2025). "The red cell distribution width‐to‐albumin ratio (RAR) has shown promise as a prognostic marker in various conditions, yet its role in peptic ulcer perforation remains unclear." (PMID 39993970, 2025).
psoriasis (20 papers, 2016 to 2025). An autoimmune condition characterized by red, well-delineated plaques with silvery scales that are usually on the extensor surfaces and scalp. "Per Naranjo criteria, the likelihood of drug-induced psoriasis exacerbation was graded as probable for toripalimab (score=5) and possible for both albumin-bound paclitaxel and cisplatin (scores=1 each)." (PMID 40936709, 2025). "The prevalence of microalbuminuria and the mean urinary albumin excretion (an indicator of subclinical renal impairment) are higher in patients with psoriasis than in healthy controls." (PMID 31719568, 2019). "Some studies performed in patients with psoriasis have found increased urinary albumin in psoriatic patients compared with healthy controls." (PMID 29599650, 2018). "Although psoriasis is a common chronic inflammatory disorder of the skin, increasing evidence has demonstrated that psoriasis is associated with an increased risk of CKD and urinary albumin excretion." (PMID 27876003, 2016). "SeNPs produced by rGSH and bovine serum albumin inhibited various inflammation and proliferation mediated pathways and could be an ideal candidate for psoriasis therapy." (PMID 38138613, 2023). "The main indices assessed were total oxidative status, reactive oxygen species, myeloperoxidase, ischemia modified albumin, advanced glycation end-products and advanced oxidation protein products whose values were higher in subjects with psoriasis versus their healthy counterparts." (PMID 35204165, 2022). "Because of these, a study was performed in the College of Medicine, Qassim University, Buraidah, Saudi Arabia between May 2014 and February 2015 to investigate the role of ROS-induced epitopes on albumin and thyroid antigens in psoriasis autoimmunity." (PMID 33585138, 2021). "Finally, it is determined that ROS's structural alterations in albumin and thyroid antigens generate unique neo-epitopes, which could be a factor for the induction of autoantibodies in psoriasis." (PMID 33585138, 2021). "Similarly, patients with psoriasis revealed a lower ability of albumin to bind ions than healthy controls, which might be produced through an adaptive response to chronic hypoxia and oxidative stress, which might play a role in the systemic inflammation seen in psoriasis." (PMID 36009309, 2022). "We collected a data set including 466 psoriasis patients and 520 healthy controls with 81 variables from only laboratory routine tests, such as age, total cholesterol, HDL cholesterol, blood pressure, albumin, and platelet distribution width." (PMID 34665828, 2021). "In addition, CAR was more predictive of psoriasis severity than CRP, albumin, and ESR." (PMID 40172389, 2025). "Albumin, a negative acute phase protein, is reduced in chronic inflammatory states, which may contribute to the elevated NPAR observed in psoriasis patients." (PMID 40181962, 2025).
sleep disorder (20 papers, 2018 to 2026). A change from the patient's baseline sleeping pattern, in the hours slept and/or an alteration/dysfunction in the stages of sleep. "The observed association of the OBS with sleep disorders and sleep trouble was mediated by albumin, GGT, total bilirubin, and WBC." (PMID 39494313, 2024). "Some models also incorporate reversible predictors such as C-reactive protein, albumin, calcium, and parathyroid hormone to forecast the risk of sleep disorders." (PMID 39408273, 2024). "As per the univariate analysis linked to sleep disorder in LC patients, only frailty score (p < 0.0001) was found to be significantly associated with sleep disorder, while serum albumin tended to be significant (p = 0.0898)." (PMID 32764402, 2020). "The interaction between sleep disorders and anxiety-like behavior may be closely linked to the dysfunctional transportation of thyroid hormones by albumin." (PMID 40427032, 2025). "This study, based on the NHANES database, is the first to delve into the mediating roles of inflammatory response (hs-CRP, WBC, SII, and SIRI) and oxidative stress (GGT, albumin, ferritin, and total bilirubin) in the association between sleep disorder and infertility risk." (PMID 40270512, 2025). "Therefore, the underlying mechanism of the interaction between sleep disorders and anxiety-like behavior may be closely related to dysfunctional albumin transport of thyroid hormones." (PMID 40427032, 2025). "Additionally, the sleep disorder group showed significantly lower levels of body mass index, peripheral albumin, prealbumin, hemoglobin, and transferrin than the normal sleep group (all P < 0.001)." (PMID 41584611, 2025). "However, in this study, we were unable to establish a connection between albumin, ferritin, sleep disorder and infertility." (PMID 40270512, 2025). "Moreover, the relationships between OBS and both sleep disorders and trouble were influenced by albumin, γ-glutamyl transferase, total bilirubin, and white blood cells, with combined mediation effects of 34.66 and 29.54%, respectively (both p < 0.001)." (PMID 39494313, 2024). "As per the univariate analysis linked to sleep disorder (PSQI-J score 6 or greater) for all cases, age (p = 0.0111), and frailty score (p < 0.0001) were found to be significantly associated with sleep disorder, while ALBI score (p = 0.0825) and serum albumin (p = 0.0708) tended to be significant." (PMID 32764402, 2020). "LASSO regression analysis and multivariate logistic regression identified gender, age, NIHSS score, cervical spondylosis, sleep disorders, fasting blood glucose (FBG), and albumin (ALB) as significant predictors." (PMID 40400911, 2025). "Compared with normal sleep group, the sleep disturbances group demonstrated older age, longer duration, higher H-Y stage, UPDRSIII score, lower MNA score, PDSS score, BMI, hemoglobin, total protein, albumin and prealbumin (all p < 0.05)." (PMID 41551321, 2025). "Multiple mediation analysis showed that all the potential biomarkers (albumin, GGT, bilirubin, and WBC) combined mediated 34.66 and 29.54% of the total relationship for sleep disorders and sleep trouble, respectively." (PMID 39494313, 2024). "Specifically, separate mediation analyses revealed that albumin mediated 24.55 and 12.97% of the total relationship between the OBS and sleep disorders and sleep trouble, respectively." (PMID 39494313, 2024). "A study found that serum albumin levels were significantly lower in patients with sleep disorders than in those without sleep disorders." (PMID 35655296, 2022). "There was significant difference between PD patients with sleep disturbances and those without in age, duration, H-Y stage, UPDRSIII, MNA, BMI, hemoglobin, total protein, albumin and prealbumin (all P < 0.05)." (PMID 41551321, 2025).